RNU4-28P (RNA, U4 small nuclear 28, pseudogene)
Gene: Small nuclear RNA gene on chromosome 1 (19,510,593 to 19,510,733, forward strand). Ensembl gene ENSG00000201609.
Homologues: Orthologues: chimpanzee U4 (93% identical). Paralogues in human: RNU4-10P (77% identical), RNU4-32P (73% identical), RNU4-79P (73% identical), RNU4-49P (70% identical), RNU4-15P (68% identical), RNU4-90P (68% identical), RNU4-50P (67% identical), RNU4-81P (67% identical), RNU4-83P (66% identical), RNU4-17P (65% identical), RNU4-75P (65% identical), RNU4-36P (65% identical), and 80 more.